IGF1 (insulin like growth factor 1)
Diseases named in the same sentence as IGF1 in open-access papers (continued):
Sharing a sentence is not in itself a finding about the gene and the disease.
Hyperglycemia (continued). "GHR-KO;RIP::IGF-1 mice are capable of inducing a greater transcriptional (or possibly translational, but probably not simply secretory) insulin action response to hyperglycemia than standard GHR-KO mice when challenged with a glucose load under AL-fed conditions." (PMID 25244225, 2014). "Maternal hyperglycemia did not change serum IGF-1 levels in DOL 21 OHM." (PMID 22548154, 2012). "However, systemic treatment with IGF-1 did not prevent hyperglycemia in diabetic rats." (PMID 40362202, 2025). "Moreover, the patient had a normal IGF-1 and elevated GH that was not suppressed by hyperglycemia." (PMID 36874742, 2023). "Reduced IGF-1 expression in DRG was also observed in the pre-diabetic HFD mouse model, suggesting hyperglycemia per se was not a sole trigger of reduced CEBPβ function." (PMID 35298717, 2022). "Other factors that link hyperglycemia to ROP, including low blood IGF-1 level, use of insulin therapy were not addressed in our study." (PMID 25766465, 2015). "Furthermore, the increase in PlGF release in response to hyperglycaemia was lost in HUVEC following knock-down of FOXO1, and no IGF-1-mediated suppression of PlGF production was observed in the presence of constitutively active FOXO1." (PMID 34381074, 2021). "Studies imply that sensory complications of diabetic polyneuropathy can be corrected by raising circulating IGF-1 levels to a physiological standard by either a gene or a protein therapeutic, or by agents that can serve to up-regulate IGF-1 without correcting hyperglycemia." (PMID 30983995, 2019). "Although IGF-1 levels are increased in fetal serum in diabetic pregnancy and IGF-1 is considered to be a major factor promoting cardiac growth, its expression was not altered in hyperglycemia hearts in our model." (PMID 26064981, 2015).
sarcopenia (315 papers, 2007 to 2026). Progressive decline in muscle mass due to aging which results in decreased functional capacity of muscles. "Endocrinologically, declines in sex hormone levels, impaired insulin/IGF-1 signaling, and vitamin D deficiency collectively contribute to the progression of sarcopenia." (PMID 41140691, 2025). "With aging and the progression of chronic disease, IGF-1 expression and activity decline markedly, a change closely associated with the development of sarcopenia." (PMID 41140691, 2025). "Changes in myostatin, IGF-1, follistatin, and creatine kinase levels have been shown to be linked with COVID-19-related sarcopenia." (PMID 40943488, 2025). "It has been reported that the age‐induced decrease in IGF‐1 secretion is associated with sarcopenia, muscle frailty, and upper extremity obesity." (PMID 39764565, 2025). "Of note, decreased IGF-1 expression is associated with aging, and even sarcopenia is related to an impaired IGF-1 signaling pathway." (PMID 40809315, 2025). "In males aged 60 and above, the secretion of IGF-1 decreases with age, which is closely associated with the development of sarcopenia and muscle weakness." (PMID 40926887, 2025). "A Mendelian randomization study based on genetic evidence further suggests a causal association between genetically predicted higher IGF-1 levels and lower sarcopenia risk." (PMID 40917423, 2025). "SPARC’s activation is mediated through the phosphatidylinositol 4,5-bisphosphate 3-kinase (PI3K) signaling pathway linked to Insulin-like Growth Factor 1 (IGF-1), making it vital for the prevention of sarcopenia." (PMID 40076821, 2025). "In contrast, lower levels of IGF-1 are associated with heightened risks of sarcopenia, cardiovascular disease, and functional decline among older people." (PMID 41011088, 2025). "Sarcopenia has been linked to reduced levels of anabolic hormones, specifically insulin-like growth factor 1 (IGF-1), among individuals aged 60 years and above." (PMID 41004429, 2025). "Lower IGF-1 has been correlated with reduced muscle mass, poor physical performance, and increased muscle weakness—hallmark features of sarcopenia." (PMID 40944148, 2025). "As a result, we successfully identified a causal effect between IGF family members and sarcopenia, with higher levels of IGF-1, IGF-1R, IGFBP-3, and IGFBP-7 being associated with a reduced risk of sarcopenia." (PMID 39507055, 2024). "We investigated if those suggestive variants are associated with sarcopenia-related traits such as lean body mass, frailty, walking pace fatigue, testosterone and IGF1 in the UK Biobank." (PMID 38769351, 2024). "Lower levels of insulin-like growth factor-1 expression in sarcopenia have been linked to muscle denervation, as well as poor neuronal regeneration, potentially contributing to the onset of sarcopenia." (PMID 39345878, 2024). "Studies have provided evidence supporting the association between sarcopenia and reduced IGF-1 signaling, namely the isoform IGF-1Ec, also known as MGF." (PMID 37815907, 2024). "Some studies revealed a significant relationship between myokine and phenotype of sarcopenia and/or physical frailty, such as myostatin and IL-15 associated with muscle weakness and/or wasting, IGF-1 with muscle weakness, slowness, disability." (PMID 38375321, 2024). "Consistent with the direction of action of IGF-1, it increases muscle mass and reduces the risk of sarcopenia, as verified by our findings." (PMID 39507055, 2024). "In chronic sarcopenia, biomarkers associated with sarcopenia prevalence include myostatin, inflammatory cytokines, and Growth Hormone (GH)/Insulin-like Growth Factor 1 (IGF-1)." (PMID 39012665, 2024). "It has been postulated that myostatin causing catabolism in males and reduced IGF-1 leading to anabolic decline in females have a role in the sex differences in sarcopenia development." (PMID 38285652, 2024).
sarcopenia (continued). "A reduction in circulating IGF-1 levels was associated with a decline in cognitive function and sarcopenia in humans." (PMID 37881503, 2023). "Our previous study revealed an association between low serum IGF-1 levels and sarcopenia and low gait speed in patients with cirrhosis." (PMID 37780552, 2023). "Other factors that are associated with the development of sarcopenia include a reduced level of growth hormone (GH), insulin-like growth factor (IGF-1) and androgens, which are related to the development of skeletal muscle." (PMID 37928789, 2023). "According to the 2014 AWGS criteria, a history of falls in the past year, IGF-1 levels, osteoporosis, and severe sarcopenia were associated with fragility fracture." (PMID 37775530, 2023). "Another study showed that higher serum myostatin levels were associated with sarcopenia in males, while in females, lower serum IGF1 levels were associated with sarcopenia." (PMID 36820956, 2023). "Results from the univariate analysis revealed that age, BMI, a history of falls in the past year, serum ferritin level, hypogonadal state, CTX, P1NP, IGF-1 level, and severe sarcopenia were associated with osteoporosis." (PMID 37775530, 2023). "In recent years, decreased levels of IGF-1 have been found to be associated with sarcopenia in various disease states." (PMID 36819699, 2023). "Twelve weeks of circuittraining had a positive effect on the improvement in cardiovascular risk factors,vascular inflammatory markers, and IGF-1 in elderly obese women with sarcopenia." (PMID 39076242, 2022). "Sarcopenia is also frequently associated with reduced circulating levels of IGF-1, which has been indicated as a possible biomarker for the condition." (PMID 36430301, 2022). "We have previously reported that low IGF-1 levels were associated with sarcopenia (defined as a loss of skeletal muscle mass and strength) and impaired physical performance in patients with cirrhosis." (PMID 36010307, 2022). "In an in vivo study, IGF-1 activated a series of anabolic and compensatory pathways, which prevented muscle loss and normal muscle‐nerve interaction, counteracting sarcopenia." (PMID 35371569, 2022). "Previous reports have shown that lower IGF-1 blood levels are associated with frailty and sarcopenia in older persons, as well as cardiovascular disease, diabetes mellitus, cancer, and cognitive impairment." (PMID 35948948, 2022). "Decreased IGF-1 expression is reported in experimental models of aging, indicating that sarcopenia is associated with an inhibited IGF-1 signaling pathway." (PMID 35053303, 2022). "This study investigated the effects of a 12-week circuit training program oncardiovascular risk factors, vascular inflammatory markers, and IGF-1 in elderlyobese women with sarcopenia." (PMID 39076242, 2022). "Nevertheless, in a further stage of aging, a deficit of insulin-like growth factor-1 and testosterone hormone levels appears in men’s blood, causing a higher speed of muscle function and mass loss, resulting in sarcopenia." (PMID 36231280, 2022). "The GH-IGF-1 axis has long been considered a beneficial factor for skeletal muscle growth, while a decrease in the production of IGF-1 is associated with sarcopenia." (PMID 35770017, 2022). "This studyattempted to investigate the effects of cardiovascular risk factors, vascularinflammatory markers, and IGF-1 on obese women with sarcopenia by conductingcircuit training selected as the latest trend for 12 weeks." (PMID 39076242, 2022). "Insulin-like growth factor-1 (IGF-1) is an important ligand for growth hormone (GH) to exert its physiological effects, and decreased GH and IGF-1 levels are associated with impaired physical performance and sarcopenia." (PMID 36261756, 2022). "On univariate analysis, the following nine factors were associated with sarcopenia: age, BMI, LC, albumin, IGF-1, BCAA, osteoporosis, prevalent fracture, and high fracture risk." (PMID 34575191, 2021).
sarcopenia (continued). "The lowest IGF-1 concentrations were linked with sarcopenia in men and women in another large study of 396,707 participants (68.8% women, ages 38 to 73 years) from the UK Biobank (EWGSOP2 criteria)." (PMID 34943268, 2021). "Collectively, these data provide support for the idea that habitual protein intake influences IGF-1 levels, a finding made relevant by established associations between IGF-1 and both appendicular muscle mass and sarcopenia." (PMID 33672207, 2021). "Recently, we have reported that decreased levels of BCAA and IGF-1 were significant, independent factors associated with sarcopenia in patients with LC." (PMID 33050430, 2020). "We are unaware of any previous systematic reviews that have investigated the importance of micronutrient intakes on sex hormones and IGF-1 in middle and older aged people at risk of sarcopenia." (PMID 32443563, 2020). "Other studies reported that lower IGF-1 levels were associated with sarcopenia and deteriorated physical performance in older adults." (PMID 33050430, 2020). "We investigated the association of serum BCAA and IGF-1 levels with sarcopenia and gait speed in 192 patients with liver cirrhosis (LC)." (PMID 33050430, 2020). "This study aimed to evaluate the GH/IGF-1 axis in the pathogenesis of sarcopenia and to identify factors associated with it." (PMID 32264885, 2020). "Low serum BCAA and IGF-1 levels were associated with sarcopenia and slow gait speed in patients with LC." (PMID 33050430, 2020). "Since the age-related decline in sex-hormones and IGF-1 not only increases the risk of sarcopenia, but also a number of conditions of aging, including falls, osteoporosis, fractures, cardiovascular disease and all-cause mortality, this is unfortunate." (PMID 32443563, 2020). "The purpose of the study was to understand the factors associated with sarcopenia and the role of GH and IGF-1 in the occurrence of sarcopenia." (PMID 32264885, 2020). "In the present study, decreased levels of BCAAs and IGF-1 were significant independent factors associated with sarcopenia." (PMID 31878909, 2019). "Taken together, our results are theoretically reasonable and support the notion that decreased levels of both BCAA and IGF-1 are associated with the development and progression of sarcopenia in patients with LC." (PMID 31878909, 2019). "Sarcopenia is associated with age-related hormonal changes (decreased growth hormone/insulin-like growth factor [GH/IGF-1] and testosterone) and reduced activity (due to a sedentary lifestyle or osteoarthritis)." (PMID 30619872, 2018). "The role of IGF1 and its related molecules in the maintenance of skeletal muscle mass in humans is especially important for elderly individuals whose IGF1 levels decrease with age and are at risk of frailty and sarcopenia." (PMID 28203146, 2017). "GH and IGF-1 levels progressively decline in aging and are important contributors to age-associated osteopenia and sarcopenia." (PMID 28459884, 2017). "Certainly, IGF1 has been of particular interest in aging research over the years, and low circulating levels of IGF1, particularly in combination with elevated IL-6, have been associated with decreased muscle strength and increased prevalence of sarcopenia." (PMID 26856410, 2016). "Declines in the circulating levels of specific hormones (e.g., estrogens, testosterone, growth hormone, insulin-like growth factor-1 (IGF-1)) have been demonstrated to be associated with sarcopenia and seem to have an important role in its pathogenesis." (PMID 22535191, 2013). "Alterations in SCFAs production have been associated with changes in IGF-1 signaling and inflammatory status, which may be relevant to sarcopenia-related mechanisms." (PMID 41598223, 2026).
sarcopenia (continued). "However, some studies have suggested a potential role for irisin in muscle health, showing lower levels in individuals with sarcopenia and positive associations with muscle mass, handgrip strength or IGF‐1 expression." (PMID 41457869, 2026). "In addition, IGF-1 deficiency has been associated with sarcopenia, premature atherosclerosis, endothelial dysfunction, increased inflammation, and plaque instability." (PMID 41598223, 2026). "In general, reduced IGF-1 levels in CKD may be associated with the degree of sarcopenia often present in these patients." (PMID 41566102, 2026). "It has also been reported that insulin-like growth factor-1 (IGF-1), which activates muscle protein synthesis, has lower blood levels in the sarcopenia group than in the non-sarcopenia group, and that there is an association between muscle mass and muscle strength and IGF-1." (PMID 39940810, 2025). "After the age of 21, serum IGF-1 concentrations in humans show a progressive downward trend with increasing age, and this decline is closely associated with the onset and progression of sarcopenia." (PMID 40917423, 2025). "Insulin-like growth factor-1 (IGF-1) is thought to play an important role in regulating skeletal muscle mass and function, with its decline potentially linked to age-related frailty and sarcopenia." (PMID 40917423, 2025). "Because IGF-1 is a key anabolic factor for muscle protein synthesis, reduced circulating or tissue IGF-1 in severe or protracted COVID-19 may contribute to sarcopenia and muscle loss." (PMID 40943488, 2025). "The steroidogenic theory of sarcopenia has been linked to changes in insulin-like growth factor-1 (IGF-1), a principal anabolic myokine, and development of depression has been linked to both low and high, but not median, circulating IGF-1 levels in elderly populations." (PMID 39286983, 2024). "Heart disease may cause sarcopenia through common pathogenetic pathways, including inflammation, insulin-like growth factor-1, angiotensin, sex hormones, myostatin, physical inactivity, low EF, and malnutrition." (PMID 38737730, 2024). "Moreover, in sarcopenia and frailty conditions, the age-related low signalling of GH, IGF-1, and other hormones are associated with their incidence and pathogenesis." (PMID 36985374, 2023). "Similarly, several studies found that sarcopenia was associated with Insulin-like growth factor 1 only in women, which was able to enhance muscle mass and strength, reduce degeneration, inhibit long-term and excessive inflammatory processes." (PMID 36615879, 2023). "Reduced levels of IGF‐1 (Insulin‐like growth factor 1) simultaneously during a lifetime may be another explanation for the potential association between probiotics and sarcopenia." (PMID 37701185, 2023). "Thus, low IGF-1 is an important independent factor associated with age- and disease-related sarcopenia." (PMID 38024081, 2023). "In addition, studies have suggested that levels of growth hormone (GH), insulin-like growth factor-1 (IGF-1), and testosterone play a role in the association between sarcopenia and sleep disorders." (PMID 37587447, 2023). "This theory suggests that circulating angiotensin II is associated with muscle wasting, reduced IGF-1 levels and insulin resistance and, therefore, could potentially contribute to the development of sarcopenia." (PMID 37928789, 2023). "IGF-1 is known to enhance muscle mass and alleviate sarcopenia, and low serum IGF-1 levels could increase the risk of idiopathic osteoporosis." (PMID 35328013, 2022). "A decline in IGF-1 may be also indicative of the development of sarcopenia, which is characterized by a progressive and general loss of skeletal muscle mass and strength." (PMID 35978214, 2022). "Indeed, impaired action of insulin/IGF-1 signaling is counted among the potential mechanisms underlying the development of sarcopenia, a major phenomenon associated with aging, which is characterized by decreased mass and impaired function of skeletal muscle." (PMID 36198696, 2022).